KLF4 (KLF transcription factor 4)
Diseases named in the same sentence as KLF4 in open-access papers (continued):
Sharing a sentence is not in itself a finding about the gene and the disease.
Hydrocephalus (3 papers, 2018 to 2024). Hydrocephalus is an active distension of the ventricular system of the brain resulting from inadequate passage of CSF from its point of production within the cerebral ventricles to its point of absorption into the systemic circulation. "Klf4 dysregulation is associated with hydrocephalus phenotypes seen in transgenic mice with Klf4 selectively overexpressed in NPCs19." (PMID 29374155, 2018). "Moreover, down-regulation of KLF4 was previously noted in neural stem cells for mediation of axonal regeneration, and further highlighted to be of great importance to neural development, while dysregulation of KLF4 is known to precipitate hydrocephalus." (PMID 34422795, 2021). "In this regard, KLF4 dysregulation may lead to hydrocephalus." (PMID 37996730, 2024).
inflammatory bowel disease (3 papers, 2018 to 2025). A spectrum of small and large bowel inflammatory diseases of unknown etiology. "Kruppel-like factor 4 (KLF4) is a transcription factor characterized by a zinc-finger (ZNF) structure, and it is implicated in the pathogenesis of various inflammatory diseases, including inflammatory bowel disease, OA, kidney inflammation, pneumonia, and neuroinflammation." (PMID 40520234, 2025).
liver disease (3 papers, 2012 to 2022). "These evidences further identify the critical role of USP11/KLF4 axis in the occurrence and development of different liver diseases, which might be a potential target for the treatment of various liver-origin diseases." (PMID 35715413, 2022). "Interestingly, two of those data sets showed a trend of gradual decrease of KLF4 mRNA expression with liver disease progression: Wurmbach’s data set (GSE14520) showed consistent reduction of KLF4 mRNA in samples from tissues of normal, cirrhosis, dysplasia, to HCC in a stepwise manner." (PMID 22937066, 2012). "Our functional results provide evidence for the crosstalk between KLF4 and USP11 in hepatic diseases; in particular, they show how USP11 enhances HCC tumorigenesis and steatosis through KLF4 inhibition." (PMID 34114341, 2021). "More importantly, we demonstrated the negative correlation between KLF4 and USP11 expression in liver diseases such as non‐alcoholic fatty liver disease (NAFLD) and HCC." (PMID 34114341, 2021).
Lung Injury (3 papers, 2020 to 2025). "It has been shown that KLF4 can play a protective role in acute lung injury, and upregulating KLF4 enhances the pathological state and inflammatory response in LPS‐induced acute lung injury in mice." (PMID 40042137, 2025). "Recent studies suggest that KLF4 promotes TBI-induced nerve injury." (PMID 34422795, 2021).
metastatic melanoma (3 papers, 2017 to 2020). A melanoma that has spread from its primary site to another anatomic site. "Using the same iPSC markers, we have also shown the presence of two CSC subpopulations within head and neck metastatic malignant melanoma (HNmMM): an OCT4+/SOX2+/KLF4+/c-MYC+ CSC subpopulation within the TNs, and another in the PTS with NANOG present only in two of the 20 cases studied." (PMID 32850316, 2020). "Focusing on KLF4, a component of the sonic hedgehog signaling pathway noted to be activated in metastatic melanoma from TCGA, we confirmed the anti-correlation between T cell-inflamed gene expression and pathway gene expression (P = 0.002, Pearson’s correlation)." (PMID 33106165, 2020).
polycystic ovary syndrome (3 papers, 2020 to 2023). A disorder that manifests as multiple cysts on the ovaries. "Clinical investigations point to downregulation of Klf4 expression in the ovaries of patients with polycystic ovary syndrome (PCOS)." (PMID 33036290, 2020). "Also, clinical investigations point to dysregulation of Klf4 and Cyp17A1 expression in the ovaries of patients with polycystic ovary syndrome (PCOS)." (PMID 38255178, 2023).
rectum adenocarcinoma (3 papers, 2020 to 2021). An adenocarcinoma arising from the rectum. "We used UALCAN to study which genes in rectal adenocarcinoma are related to the expression of KLF4 or KLF5." (PMID 34367275, 2021). "This is the case for rectum adenocarcinoma: its five oncogenes are BCL2, KIT, KLF4, MET, and PDGFRA." (PMID 31900418, 2020).
Secretory Meningioma (3 papers, 2023 to 2025). A WHO grade I meningioma characterized by the presence of epithelial differentiation and numerous intracellular PAS positive bodies that are rich in glycogen. "Mutations in AKT1, KLF4, POLR2A or SMO were mostly detected in meningothelial or transitional meningioma, except for three cases: one case of angiomatous meningioma with KLF4 mutation, one case of secretory meningioma with KLF4 mutation and one case of psammomatous meningioma with AKT1 mutation." (PMID 40815185, 2025).
steatosis (3 papers, 2012 to 2021). Increased lipid within the cytoplasm of cells. "We observed that KLF4 expression dramatically decreased while USP11 increased in in vitro steatosis conditions induced by FFA treatment." (PMID 34114341, 2021). "HE staining revealed serious hepatocellular steatosis in the CCl4-injected mice, and KLF4 alleviated this steatosis in the mice injected with KLF4 plasmid." (PMID 31687083, 2019). "Retroviruses encoding the reprogramming factors, OCT4, SOX2, KLF4, and c-MYC were transduced into fibroblasts cells from patient with steatosis (H0008) and control (H0002) using well established protocols." (PMID 22969728, 2012).
Streptococcus pneumoniae Infection (3 papers, 2018 to 2025). "In Streptococcus pneumoniae infections, KLF4 enhances early inflammation and bacterial clearance, whereas in Pseudomonas aeruginosa infections, it prevents excessive immune activation, and in Mycobacterium infections, it promotes bacterial persistence." (PMID 40313940, 2025). "In Streptococcus pneumoniae infection, KLF4 expression is upregulated in neutrophils through direct contact with viable pneumococci." (PMID 40313940, 2025). "In this study, we focused on the S. pneumoniae-dependent induction mechanism of KLF4 in macrophages and the possible influence of KLF4 on the macrophage inflammatory cytokine response during a pneumococcal infection." (PMID 29636524, 2018).
systemic sclerosis (3 papers, 2021 to 2026). A chronic disorder, possibly autoimmune, marked by excessive production of collagen which results in hardening and thickening of body tissues. "However, KLF4 is upregulated in fibrotic skin and lungs from mice with systemic sclerosis." (PMID 33929970, 2021).
allergic rhinitis (2 papers, 2023 to 2024). Inflammation of the nasal mucous membranes caused by an IgE-mediated response to external allergens. "Besides, KLF4 regulates immune response-related genes including IL1RL1, CD274, and CD44 in human nasal epithelial cells of allergic rhinitis." (PMID 38245772, 2024).
anaplastic meningioma (2 papers, 2018 to 2019). A WHO grade III meningioma characterized by the presence of malignant morphologic features, including malignant cytology and a very high mitotic index (20 or more mitoses per ten high power fields). "Interestingly, KLF4 expression was high in benign tumors, but low in anaplastic meningiomas: KLF4 expression in anaplastic tumors resulted in suppression of tumor growth." (PMID 30279357, 2018).
Angiomatous Meningioma (2 papers, 2014 to 2025). A WHO grade I meningioma characterized by the presence of small and medium sized vessels that predominate over the meningioma cells. "To determine if established cancer genes are mutated in angiomatous meningioma, we sequenced all exons from 560 cancer associated genes and performed amplicon sequencing of all exons from TRAF7 and the exon encoding the KLF4 K409 amino acid residue that were not present in the OPv2 gene set." (PMID 25347344, 2014).
Anxiety (2 papers, 2020 to 2023). Intense feelings of nervousness, tension, or panic often arise in response to interpersonal stresses. "Studies on inflammation and oxidative stress have shown that KLF4 may cause anxiety through changes in the physiology of the brain." (PMID 36979479, 2023).
astrocytoma (2 papers, 2011 to 2022). "Transcripts of the embryonic stem cell markers Oct4, Nanog, and - at low levels - Klf4 were detected in the four tumor cultures examined (one astrocytoma II, two astrocytoma III and one oligoastrocytoma III that yielded cell-forming spheres with extended self-renewal properties)." (PMID 21297991, 2011). "Infection with RVFV induced significant upregulation of ATF3, FOS, KLF4, CXCL10, TNF-α, and PTGS2 in astrocytoma cells at 16 hpi." (PMID 35746681, 2022).
brain cancer (2 papers, 2023 to 2024). A primary or metastatic malignant neoplasm affecting the brain. "Moreover, the regulatory role of KLF4 has been described in a wide number of cancers, such as lung, breast, prostate, colorectal, brain cancer and more." (PMID 38794128, 2024). "Evidently, KLF4 plays an important role in the vast majority of tumors, including lung, breast, prostate, colorectal, pancreatic, liver, ovarian, esophageal, bladder, and brain cancers." (PMID 37031197, 2023). "Currently, the role of KLF4 in different subtypes of brain cancer is yet to be defined." (PMID 37031197, 2023). "It has been investigated that KLF4 has a regulatory role in a variety of cancers, including lung, breast, prostate, colorectal, pancreatic, hepatocellular, ovarian, esophageal, bladder and brain cancer." (PMID 37031197, 2023).
breast adenocarcinoma (2 papers, 2019 to 2022). "In human breast adenocarcinoma cells, reduced susceptibility to CTL-mediated lysis depended on upregulation of the stem cell marker Kruppel-like factor-4 (KLF-4) and miR-7 downregulation." (PMID 31096701, 2019).
cervical (2 papers, 2020 to 2021). "Our results show that Oct4, as well as other stemness markers such as Sox2 and Klf4, are indeed enriched in the cervical tumorspheres compared to the cancer cell monolayers and this was true in all conditions tested." (PMID 32298395, 2020). "The array data analysis performed with GEO2R showed that the expression of CBP/β-catenin and its target genes of KLF4, MYC, and SOX2 were upregulated, generally synchronicity with the progression of cervical lesion grade." (PMID 34257574, 2021).
chondrosarcoma (2 papers, 2022 to 2023). A malignant cartilaginous matrix-producing mesenchymal neoplasm arising from the bone and soft tissue. "Specifically, overexpression of miR-34a enables chondrosarcoma cells to overcome resistance to carbon-ion irradiation by upregulating FOXO3, which leads to KLF4 repression." (PMID 36326232, 2022).
Cognitive impairment (2 papers, 2024 to 2026). Abnormal cognition is characterized by deficits in thinking, reasoning, or remembering. "miR-25802 orchestrates the KLF4/NF-κB pathway in microglia-mediated neuroinflammation, facilitating cognitive impairments and Aβ toxicity, highlighting the potential of targeting miR-25802 and its regulatory network as an emerging frontier in AD treatment." (PMID 39759526, 2024). "Consistently, KLF4 overexpression or silencing in 5×FAD mouse brain reversed the pathological characteristics associated with miR-25802 upregulation or inhibition, including cognitive impairment, Aβ deposition, microglial activation, and inflammatory reactions." (PMID 39759526, 2024). "Because KLF4 levels in ECs decrease with age, we tested whether that decline contributes to aging-related BBB deterioration, neurovascular dysfunction, and cognitive impairment." (PMID 42313933, 2026).
Crohn disease (2 papers, 2007 to 2017). A gastrointestinal disorder characterized by chronic inflammation involving all layers of the intestinal wall, noncaseating granulomas affecting the intestinal wall and regional lymph nodes, and transmural fibrosis. "It has been shown that the zinc finger transcription factor Klf4 is required for the differentiation of colonic goblet cells and is induced during mucosal inflammation in Crohn’s disease." (PMID 29042502, 2017).
dementia (2 papers, 2020 to 2023). Loss of intellectual abilities interfering with an individual's social and occupational functions. "Given the involvement of KLF4 in apoptosis and neuroinflammation, follow up mechanistic studies evaluating its potential as a therapeutic target for dementia will be valuable." (PMID 32192109, 2020). "Finally, Venn analysis identified kruppel-like factor 4 (KLF4) as the only transcription factor shared between the 3 dementias." (PMID 32192109, 2020).
diabetic cardiomyopathy (2 papers, 2024). Diabetic cardiomyopathy is a disorder of the heart muscle in people with diabetes. "Additionally, KLF4 upregulation exacerbates cardiomyocyte autophagy; hence, aggravating diabetic cardiomyopathy." (PMID 38516000, 2024).
diffuse large B-cell lymphoma (2 papers, 2020 to 2025). "Moreover, in follicular lymphoma (FL), diffuse large B-cell lymphoma (DLBCL), and BL, low KLF4 expression is likely a prerequisite for high MSC/ABF-1 expression." (PMID 39995670, 2025).
Duchenne muscular dystrophy (2 papers, 2018 to 2023). Duchenne muscular dystrophy (DMD) is a neuromuscular disease characterized by rapidly progressive muscle weakness and wasting due to degeneration of skeletal, smooth and cardiac muscle. "Moreover, the expression of KLF4 in skeletal muscles in Duchenne muscular dystrophy (DMD) mice was significantly higher than that in (wild-type) WT mice (GSE162455)." (PMID 37723138, 2023). "The DYS-HAC was transferred to Duchenne muscular dystrophy patient-derived fibroblasts from CHO cells, from which iPSCs were generated using a combination of lentiviral infection for expressing mouse SLC7A1 and retroviral infection for expressing KLF4, SOX2, OCT4, and c-MYC." (PMID 32161806, 2018).
dyslipidemia (2 papers, 2016 to 2020). "The findings suggest that, in obese status, the lower expression level of A2bAR, KLF4, and KLF15 of visceral adipose tissue may correlate with obese-dyslipidemia induced inflammation in Uygur population." (PMID 27199507, 2016).
experimental autoimmune encephalomyelitis (2 papers, 2020 to 2025). An autoimmune demyelinating disease of the central nervous system that is produced experimentally in animals by the injection of homogenized brain or spinal cord in Freund's adjuvant. "CD16+ monocytes showed downregulation of select transcription factor genes (RXRA, IKZF1, KLF4, IRF4) and CD81, a marker that facilitates monocytes homing to the CNS in experimental autoimmune encephalomyelitis (EAE)." (PMID 40067358, 2025). "The authors report the surprising and potentially therapeutically interesting finding that removing Klf4 specifically from retinal neurons has a protective effect on Retinal Ganglion Cell (RGC) survival and function in experimental autoimmune encephalomyelitis (EAE)." (PMID 32165410, 2020).
Familial adenomatous polyposis (2 papers, 2009 to 2023). Familial adenomatous polyposis (FAP) is characterized by the development of hundreds to thousands of adenomas in the rectum and colon during the second decade of life. "KLF4 is decreased in both adenomas from multiple intestinal neoplasia (ApcMin/+) mice and humans with familial adenomatous polyposis (FAP) when compared to either normal-appearing intestinal tissue from the same individual or healthy controls." (PMID 37173904, 2023).
gastric adenoma (2 papers, 2024). A neoplastic polyp that arises from the stomach. "Recent studies have demonstrated that KLF4 mutation plays an important role in the pathologic characteristics of foveolar-type gastric adenoma in Helicobacter pylori-naive patients." (PMID 39133395, 2024). "Research has discovered a prevalent SNV in the zinc finger 2 region of the KLF4 gene in the foveolar-type gastric adenoma (FGA) tissues of Helicobacter pylori-negative patients." (PMID 38870270, 2024).
glaucoma (2 papers, 2021). Increased pressure in the eyeball due to obstruction of the outflow of aqueous humor. "The use of the Oct4 (also known as Pou5f1), Sox2 and Klf4 genes (OSK) to reverse DNA methylation during glaucoma and restore vision strongly suggest that PRC2 may be involved in glaucoma as well." (PMID 34502238, 2021).
glomerular diseases (2 papers, 2023 to 2024). "Kruppel-like factor 4 (KLF4), which is expressed in podocytes, has been observed to decrease in glomerular diseases, leading to the methylation of the nephrin promoter, decreased nephrin expression, and the development of proteinuria." (PMID 38671903, 2024). "KLF4, KLF6, and KLF15 were also shown to be expressed in glomerular podocytes, and their protein expression levels were significantly reduced in injured podocytes in proteinuria glomerular diseases 31-35." (PMID 36632460, 2023).
Hepatic steatosis (2 papers, 2021 to 2024). Steatosis is a term used to denote lipid accumulation within hepatocytes. "Finally, elevated USP11 and reduced KLF4 levels were detected both in a hepatic steatosis in vitro model and in public clinical data of non‐alcoholic fatty liver disease and HCC patients." (PMID 34114341, 2021).
Hirschsprung disease (2 papers, 2023 to 2024). Hirschsprung disease (HSCR) is a congenital intestinal motility disorder that is characterized by signs of intestinal obstruction due to the presence of an aganglionic segment of variable extent in the terminal part of the colon. "The has-mir-92a represses the viability and migration of nerve cells in Hirschsprung’s disease by regulating the KLF4/PI3K/AKT pathway." (PMID 38165860, 2024).
hypertrophic cardiomyopathies (2 papers, 2024 to 2025). "For hypertrophic cardiomyopathy, the analysis showed a direct interaction, specifically co-expression and text mining, between IL-6 and KLF-2, KLF-4, and KLF-6." (PMID 38672763, 2024).
infertile (2 papers, 2021 to 2022). "Additionally, we found that WNT4, KLF4 expression level in the healthy volunteers’ group was higher than in the infertility group." (PMID 34202508, 2021).
intellectual disabilities (2 papers, 2021 to 2022). "Human fibroblast cells from a patient with infantile-onset DM1 and a severe intellectual disability and from a control patient were transformed into iPSCs using the Sendai virus technique employing Yamanaka factors (OCT4, KLF4, MYC, and SOX2)." (PMID 35075265, 2022).
Kawasaki disease (2 papers, 2018 to 2023). A rare inflammatory disease characterized by an acute febrile, systemic, self-limiting, medium-vessel vasculitis primarily affecting children. "CTGF has also been reported to promote EMT process in Kawasaki disease by regulation of KLF4." (PMID 29977158, 2018).
keratoconus (2 papers, 2021 to 2026). A degenerative, structural disorder of the eye, characterized by a cone-shaped protrusion of the cornea. "Interestingly, methylation of KLF4 was significantly (SMR p = 5.10 × 10−08) influenced by SNPs associated with keratoconus." (PMID 33649486, 2021). "Interestingly, this analysis integrated an epigenetic analysis and found that keratoconus-associated SNPs were enriched for effects on DNA methylation: for example, risk alleles at one locus significantly influenced methylation of the transcription factor gene KLF4 in corneal-relevant tissue." (PMID 41595486, 2026). "For the first time, we have identified a substantial role for cell differentiation pathways and stem cell regulators such as KLF4 and KLF5 in the pathogenesis of keratoconus, and a role for genes influencing connective tissue maturity." (PMID 33649486, 2021).
liver cirrhosis (2 papers, 2017 to 2023). "Age, liver cirrhosis, tumor number, tumor size, AFP level, tumor differentiation grade, TNM stage, and KLF4 expression were all significantly associated with OS and RFS in the univariate analysis." (PMID 36936440, 2023). "Collectively, our observation indicated that, via targeting KLF4, miR-145 could be an essential regulator in HSCs activation and in liver cirrhosis." (PMID 28091538, 2017). "The status and functions of KLF4 have not yet been investigated in HSC activation and liver cirrhosis." (PMID 28091538, 2017).